IL13 (interleukin 13)
Diseases named in the same sentence as IL13 in open-access papers (continued):
Sharing a sentence is not in itself a finding about the gene and the disease.
conjunctivitis (22 papers, 2020 to 2026). Inflammation of the conjunctiva of the eye. "Conjunctivitis is also observed with IL-13 monotherapy (lebrikizumab or tralokinumab), suggesting that IL-13 inhibition is implicated in the pathophysiology of conjunctivitis." (PMID 36626228, 2023). "Tralokinumab and lebrikizumab, which are monoclonal antibodies against IL-13, were found to be associated with an increased risk of conjunctivitis in phase 3 and phase 2 clinical trials." (PMID 34253801, 2021). "In phase III trials, all agents that inhibit IL-13, specifically dupilumab, tralokinumab, lebrikizumab, cendakimab, and eblasakimab, have been reported to have a considerably increased risk of conjunctivitis, injection site reactions, and head and neck erythema." (PMID 36839890, 2023). "Similar to dupilumab-associated conjunctivitis, this association with selective IL-13 inhibitors could be initially managed with warm compresses, artificial tears, sodium hyaluronate, or antihistamine drops while continuing the use of the biological agent." (PMID 36839890, 2023). "Dupilumab targets IL-13 action and secondary depletion of goblet cells and mucin production in the conjunctiva could be responsible for dupilumab-associated conjunctivitis." (PMID 33504973, 2021). "This pattern suggests a potential contribution of IL-4 blockade to conjunctivitis development, although further studies are warranted to delineate the specific roles of IL-4 and IL-13 in conjunctival homeostasis." (PMID 40725651, 2025). "This interleukin (IL)‐4 and IL‐13 inhibitor has extensive clinical trial and real‐world data backing its efficacy and tolerability, with the most common adverse effect being conjunctivitis." (PMID 39363512, 2025). "Other authors have confirmed that sparing IL-4 in the selective blockade of interleukin-13 in patients treated with tralokinumab leads to a smaller Th2/Th1 immune switch and a lower incidence of conjunctivitis compared to those treated with dupilumab." (PMID 38999383, 2024). "Although it appears that blocking IL-4 and IL-13 can trigger eye disorders, including conjunctivitis, there are still factors to consider about dupilumab-related eye disorders." (PMID 34253801, 2021). "The cause of dupilumab-associated conjunctivitis, as well as the relationship between its various pathogenetic mechanisms, are currently unclear, but possible hypotheses include inhibition of IL-4 and IL-13 signaling pathways involved in the development of atopic keratoconjunctivitis." (PMID 32599878, 2020). "While the pathogenesis of conjunctivitis in this setting is not completely understood, it is hypothesized to be the consequence of Demodex mite proliferation, direct IL-13-mediated reduction in goblet cells, or OX40-related inflammation." (PMID 36839890, 2023). "Concerning the mechanisms specific to ADRs and sex discrepancies, both Tralokinumab and Lebrikizumab, monoclonal antibodies targeting IL-13, have been demonstrated to correlate with elevated risks of conjunctivitis as discerned in phase 2 and 3 clinical trials." (PMID 37954855, 2023). "It is worth exploratory whether conjunctivitis results from the blockade of IL-4 and IL-13 with dupilumab or that conjunctivitis, in the first place, is part of this systemic allergic disorder." (PMID 35308529, 2022). "The IL‐13 blocking effect of dupilumab might reduce goblet cells and mucin production in some patients with AD, resulting in irritative conjunctivitis." (PMID 36125089, 2022). "Conversely, conjunctivitis and ocular pruritus were more common in the IL-13Ab group, likely due to the role of IL-13 in maintaining conjunctival goblet cell homeostasis and tear film stability; its blockade may promote ocular surface inflammation and dry eye symptoms." (PMID 40861471, 2025). "Moreover, IL-13 also plays a role in the maintenance of conjunctival well-being, hence, its inhibition may set the premises for dupilumab induced conjunctivitis." (PMID 37144036, 2023).
conjunctivitis (continued). "Because early trial data indicate that tralokinumab may be less likely to drive AOEs compared with dupilumab, for the same indications, a careful examination of real-world evidence will be necessary to establish this and whether IL-4, IL-13, or both are the drivers for the conjunctivitis observed." (PMID 36525340, 2023). "Since this drug-specific side effect had already been recognised during pre-marketing phase II–III studies and continues to be non-reported in any anti-IL-13 treated cohort, it is highly likely that conjunctivitis will not be associated with long-term IL-13 elimination." (PMID 32294982, 2020). "Lastly, regarding differentiating OX40-OX40L inhibitors from existing AD biologics in terms of safety profiles, the OX40-OX40L inhibitors do not have the adverse effect of conjunctivitis, which is related to the use of IL-4 and/or IL-13 inhibitors." (PMID 38607026, 2024). "Dupilumab (an IL-4 and IL-13 pathway inhibitor) has not been studied in AC, but one reported adverse effect of the drug is conjunctivitis, described as inflammation of the anterior conjunctiva and hyperemia of the limbus." (PMID 31993069, 2020).
myocardial infarction (22 papers, 2008 to 2025). Gross necrosis of the myocardium, as a result of interruption of the blood supply to the area, as in coronary thrombosis. "Adult mice with Il4 or Il13 deficiency experienced tissue repair impairment following myocardial infarction as judged by reduced accumulation of reparative macrophages." (PMID 38093747, 2023). "Neonatal Il4- and Il13-deficient mice showed impaired cardiac function after myocardial infarction when compared with gene-proficient mice." (PMID 38093747, 2023). "Distribution of IL-13 polymorphisms in myocardial infarction patients and healthy controls." (PMID 39088580, 2024). "However, in a recent publication that explored the mechanisms associated with wound healing following experimental myocardial infarction (MI), basophils were identified as a critical source of IL-4/IL-13 required for the healing process." (PMID 36578500, 2022). "For instance, in IL-13-knockout myocardial infarction mice, a reduction in M2 macrophages resulted in increased myocardial fibrosis and worsened heart function." (PMID 40662135, 2025). "For several years, it has been known that IL-13 is involved in cardiac wound healing and remodeling after myocardial infarction (MI)." (PMID 37629063, 2023). "For example, IL-13 can promote wound healing in myocardium after myocardial infarction, decrease LV dilation and increase LV function, and prevent heart failure." (PMID 35905078, 2022). "Similarly, previous studies have shown that macrophages induced by IL-13 exhibit high efferocytosis and anti-inflammatory activities in the functional recovery of individuals with myocardial infarction and spinal cord injury, respectively." (PMID 41460571, 2025). "It has been reported that IL-13 may also be a prognostic marker of acute myocardial infarction (AMI)." (PMID 34867998, 2021). "Recent studies appraise the role of IL‐13 in CVDs, revealing that IL‐13 is not only involved in more obvious cardiac inflammatory diseases such as myocarditis but also relevant to acute or chronic CVDs of other origins, such as myocardial infarction and heart failure." (PMID 33943014, 2021). "Oncostatin M (OSM) and IL-13 stimulate ACM cell cycle re-entry and improve cardiac function after myocardial infarction (MI) through Raf/MEK/Erk and STAT3/6 signaling pathway." (PMID 36780463, 2023). "Our results were confirmed in a very recent study in a myocardial infarction model, where overexpression of Nox4 promoted M(IL4+IL13) polarization of cardiac macrophages and protects from postinfarction remodeling." (PMID 31178956, 2019).
pneumonia (22 papers, 2012 to 2026). An acute, acute and chronic, or chronic inflammation focally or diffusely affecting the lung parenchyma, caused by an infection in one or both of the lungs (by bacteria, viruses, fungi, or mycoplasma.). "Important for therapeutic implications, and more central to our findings here, increased expression of IL-13 and IL-5 in lungs of CF patients is associated with occurrence of acute pneumonia exacerbations." (PMID 28680858, 2017). "Meanwhile, the IFN-γ/IL-13 ratio may be used to predict the risk of pneumonia and ICU hospitalization." (PMID 34692846, 2021). "Overall, during the early infection phase, AC migration led to persistent pneumonia characterized by a Th2 bias in mice (mainly IL-13 and IL-6) and rats (mainly IL-6)." (PMID 35617354, 2022). "The present study demonstrates that the Feishu point exerts therapeutic effects in pneumonia via cytokine signaling in the immune system, IL signaling, IL-4 and IL-13 signaling, and the immune system." (PMID 34306143, 2021). "Following specific activation of iNKT cells using PBMCs from patients or HV, a significant increase of cytokine secretion IFN-γ and IL-13 was observed, but only in BI patients that contracted pneumonia several days after BI." (PMID 31253189, 2019). "Strikingly, we observed a much stronger concentration of both IFN-γ and IL-13 in BI patients with pneumonia." (PMID 31253189, 2019). "In the current study, IL-33 and IL-13 were found to be significantly elevated in the pneumonia model." (PMID 24956279, 2014). "baumannii pneumonia pathogenesis via an IL-13-dependent mechanism in mice." (PMID 41660825, 2026). "Also, patients with severe pneumonia had significantly higher serum levels of IL-4, IL-5, and IL-13 than those with mild pneumonia, indicative of the role of influenza virus infection in airway type 2 inflammation." (PMID 40083723, 2025). "In our opinion, this is the first study to identify SNPs in antioxidant (SOD1, CAT, GPX1, NOS, HMOX1, and NQO1) and immunological (IL-1α, IL1B, IL6, TNF-α, IL10, LFA-1, CR2, IL17, IL13, DEFB123, SCART1, and ICAM1) genes as potential suspects for pneumonia resistance/susceptibility in Barki ewes." (PMID 40221769, 2025). "IL-13 was associated with intensive care unit (ICU) admission and protection against pneumonia." (PMID 34692846, 2021). "The Feishu point efficacy system-pneumonia system network shows that cytokine signaling in the immune system, signaling by interleukins (ILs), IL-4 and IL-13 signaling, and the immune system may be related to immunity and inflammation." (PMID 34306143, 2021). "The Feishu point efficacy system had 4 pathways that could function in pneumonia, including cytokine signaling in the immune system, signaling by interleukins (ILs), IL-4 and IL-13 signaling, and the immune system." (PMID 34306143, 2021). "The levels of several pro- and anti-inflammatory cytokines (including IL-1β, IL-6, IL-10, IL-13, G-CSF and TNFα) were examined in BAL fluid 24 hours after the onset of pneumonia in both genotypes." (PMID 23145105, 2012). "Some studies have reported that radiotherapy could prompt alveolar epithelial cells to release many cytokines, such as TNF-α, IL-6, IL-13, and TGF-β1, which in turn affect the development of pneumonia." (PMID 40821765, 2025). "Compared to pH1N1 patients without pneumonia, those who developed acute pneumonia due to pH1N1 exhibited significantly elevated levels of Th2 cytokines (IL-4, IL-5, and IL-13) in their serum." (PMID 40529241, 2025). "Our data showed that neonatal S. pneumoniae pneumonia can increase the infiltration of inflammatory cells, both in the lung tissues and in the BALF, along with releasing higher levels of the pro-inflammatory cytokines (IL-4, IL-5, IL-13, and IL-17A)." (PMID 30723734, 2019). "In addition, the levels of IL-4, IL-5, IL-13, and IL-17A in BALF were also significantly higher in the pneumonia group." (PMID 30723734, 2019).
pneumonia (continued). "Although the concentrations of IL-13, IL-17A, MIP-1α/CCL3, PAI1, sCD14, IL-1β, CCL11/eotaxin, VEGF/VPF, and RANTES/CCL5 did not exhibit significant differences between the HIV and pneumonia and HIV-only groups, several reasons could explain this lack of disparity." (PMID 38251391, 2024).
multiple sclerosis (21 papers, 2010 to 2026). A progressive autoimmune disorder affecting the central nervous system resulting in demyelination. "However, there are only few studies regarding multiple sclerosis (MS) risk and IL-13 rs20541 (R130Q) polymorphism, and their results are conflicting." (PMID 38086930, 2023). "Glatiramer acetate administration increased serum IL-5/IL-13 levels in healthy subjects, untreated multiple sclerosis patients, and those with other neurological diseases, correlating with clinical efficacy." (PMID 38612591, 2024). "The neuroprotective role of IL-13 was also found to maintain neuronal integrity and synaptic function in multiple-sclerosis patients." (PMID 35330143, 2022). "In contrast, a study on humans with multiple sclerosis found high levels of IL-13-enhanced gamma-aminobutyric acid (GABA, the dominant inhibitory neurotransmitter) over glutamate transmission." (PMID 34202937, 2021). "Lentivirus mediated IL-13 delivery promoted microglia differentiation to the M2 phenotype in a mouse model of multiple sclerosis, suggesting IL-13 gene immunotherapy is a potential treatment for neuroinflammation." (PMID 32754016, 2020). "Ongoing studies on the effects of glatiramer acetate (GA, Copaxon, formerly Copoly-mer-1) on IL-5 and IL-13 production in patients with multiple sclerosis have shown that those with a positive clinical response to treatment had elevated serum IL-5 and IL-13 levels." (PMID 39000506, 2024). "Higher levels of IL-13 may indicate increased inflammatory activity in patients with multiple sclerosis, especially in the early stages of the disease." (PMID 39000506, 2024). "A study in humans with multiple sclerosis found that high levels of IL-13 in the cerebral spinal fluid might exert a neuroprotective effect by enhancing gamma aminobutyric acid over glutamate transmission." (PMID 33801783, 2021). "In fact, IL-4, IL-10, and IL-13 high levels promote enhanced axonal regeneration, promote neuroprotection after SCI, and reduce demyelination in multiple sclerosis." (PMID 31186006, 2019). "Moreover, other groups also described elevated levels of IL-1β or IL-1β/TNF-α induced molecules like IL-1ra, IL-6, IL-8, IL-13, G-CSF, and Cxcl10 (IP-10) in the CSF of NMO patients, compared to the CSF of patients with multiple sclerosis or other neurological diseases." (PMID 24252536, 2013).
dengue (19 papers, 2007 to 2026). "It has been previously shown that pre-treatment of human monocytes with IL-4 or IL-13, increases their susceptibility to dengue virus infection in vitro." (PMID 22574162, 2012). "Type 2 cytokines such as IL-13 and IL-10 have been implicated in the pathogenesis of severe dengue." (PMID 18060049, 2007). "Several of these cytokines have been identified as markers of dengue in humans, including IL-12, IL-13, IL-17A, G-CSF, IFNγ, and TNFα." (PMID 29559699, 2018). "The AST enzyme in dengue patients with warning signs was raised throughout the illness, and this enzyme was associated (i) at the febrile phase- ICAM-1, FGF-Basic, IL-13, IL-4, IL-12 and VEGF; (ii) defervescence: PDGF and (iii) convalescence- IFN-γ and IP-10." (PMID 23284941, 2012). "We observed that cytokine concentrations of IL-1β, IFN-γ, IL-4, IL-6, IL-7, IL-13 and GM-CSF were significantly increased during severe dengue as compared to mild dengue, while MIP-1β levels are higher in mild dengue." (PMID 18578883, 2008). "The first report about an IL-18 increase in a dengue patient clinical study was published in 2001, where the results from serum examination showed high IL-13 and IL-18 in the severe illness and late dengue disease phase (over 9 days from disease onset) patients." (PMID 34840991, 2021). "On the other hand, IL-13 and IL-1β values were lower in acute dengue patients." (PMID 34734091, 2021). "In addition, IL-13 had the highest relative number of interactions in the cytokine/chemokine network of the group of dengue mono-infection." (PMID 26271921, 2015). "IL-1β, IFN-γ, IL-4, IL-6, IL-13, IL-7 and GM-CSF were significantly increased in patients with severe clinical manifestations (severe dengue) when compared to mild disease forms (mild dengue)." (PMID 18578883, 2008). "In a subsequent analysis comparing mild dengue with the combined DFWS/SD group, significantly higher exosomal levels of IL-1β, IL-5, IL-10, IL-12, IL-13, and TNF-α were observed in the DFWS/SD group (all p < 0.05)." (PMID 41993203, 2026). "Our findings reveal a distinct cytokine profile (elevated IL-8, IL-10, IL-6, GM-CSF, MCP-1, IL-13, and IL-4 and decreased IL-12, MIP-1β) on the third day after symptom onset is predictive of severe dengue in secondary dengue infection." (PMID 38176525, 2024). "•Elevated IL-8, IL-10, IL-6, GM-CSF, MCP-1, IL-13, and IL-4 and decreased IL-12, MIP-1β on the third day after symptom onset is predictive of severe dengue." (PMID 38176525, 2024). "IL-13 and MCP-3 downregulation was observed only in chikungunya patients, while conversely PDGF-AB/BB and FGF-2 downregulation was unique in dengue patients." (PMID 34215212, 2021). "By using multiplex immunoassay, we compared host cytokine profiles between acute CHIKV and DENV infections by analysing serum cytokine levels of IL-1α, IL-4, IL-5, IL-8, IL-13, RANTES, MCP-3, eotaxin, PDGF-AB/BB, and FGF-2 from the sera of acute chikungunya and dengue fever patients." (PMID 34215212, 2021). "We did not observe significant production of TNFα, IL-10, IL-4, IL-13, IL-17 by dengue NS3-specific T cells, suggesting a different source for these cytokines in the serum." (PMID 23209731, 2012). "However, one study has reported increased IL-13 in severe but not mild dengue, while another study found a moderately increased level in acute CHIKV infection." (PMID 34215212, 2021). "Increased levels of TNF-α, IL-1β, IL-4, IL-6, IL-8, IL-13, IL-15, macrophage migration inhibitory factor (MIF), and chemokines CCL2, CCL4, CCL5, and CXCL10 (IP-10) among others, have been reported in patients with dengue hemorrhagic fever (DHF) when compared to dengue fever (DF)." (PMID 29986388, 2018). "Many studies have investigated the cytokines patterns in serum samples in patients with DHF and these studies have shown that TNFα, IL-6, IL-10, IL-1β, IFN-γ, IL-4, IL-13, IL-7, GM-CSF, MIF, along with several other cytokines were elevated in patients with DHF when compared to dengue fever (DF)." (PMID 23209731, 2012).
dengue (continued). "We found that whilst patients with severe dengue had lower total T cell numbers, the DV-NS3 specific T cells persisted and produced high levels of IFNγ but not TNFα, IL-3, IL-13, IL-2, IL-10 or IL-17." (PMID 23209731, 2012). "In summary, we found that patients with severe dengue had lower T cell numbers but that DV-NS3 specific T cells produced high levels of IFNγ but not IL-3, IL-13, IL-2, IL-10 or IL-17." (PMID 23209731, 2012).